TREM2 (triggering receptor expressed on myeloid cells 2)
Diseases named in the same sentence as TREM2 in open-access papers (continued):
Sharing a sentence is not in itself a finding about the gene and the disease.
hematoma (3 papers, 2023 to 2026). A hematoma is a collection of blood from a vascular structure into an extravascular space. "Enhancing microglial/macrophage erythrophagocytosis throughactivation of TAM receptors, CD36, and TREM2 or inhibition of theSIRPα-CD47 pathway plays a central role in promoting hematoma clearanceand mitigating secondary brain injury." (PMID 41504200, 2025). "In ICH models, TREM2 knockout impairshematoma clearance and worsens neurological deficits, whereas microglia-specificoverexpression of TREM2 accelerates hematoma resolution and neurobehavioralrecovery." (PMID 41504200, 2025). "Furthermore, Sema3B enhances the interaction between PlexinA1 and TREM2, cooperatively boosting microglial phagocytosis of the hematoma after ICH." (PMID 41750601, 2026). "Furthermore, the soluble extracellulardomain of TREM2 impairs microglial/macrophage erythrophagocytosis by inhibitingvacuolar protein sorting 35-mediated CD36 recycling and promoting lysosomaldegradation of non-recycled CD36, ultimately delaying hematoma clearance andworsening neurological deficits." (PMID 41504200, 2025).
hemorrhagic stroke (3 papers, 2020 to 2025). A stroke caused by a bleed on the brain. "Although there are few reports, limited evidence suggests that TREM2 exerts some neuroprotective effects in hemorrhagic stroke." (PMID 38385036, 2024). "In recent years, several teams have investigated the role of TREM2 in hemorrhagic stroke." (PMID 38385036, 2024). "However, the potential therapeutic effects targeting TREM2 in hemorrhagic stroke have yet to be elucidated." (PMID 32466767, 2020). "Given the well‐established role of the APOE‐TREM2 axis in brain injury and hemorrhagic stroke recovery, we specifically examined the expression of APOE and TREM2 in microglia." (PMID 41363028, 2025).
hyperlipidemia (3 papers, 2019 to 2025). "Alternatively, as we used CD36 full-body deficient animals, it is also possible that adipocyte CD36 mediates the pro-inflammatory response to hyperlipidemia and restricts Trem2+ LAM via adipocyte/macrophage crosstalk." (PMID 39156133, 2024). "A potential scenario to explain the increase in Trem2+ LAM and less inflammatory macrophages in CD36 deficient mice is that ATM CD36 expression is important for a pro-inflammatory response to hyperlipidemia but is dispensable for lipid uptake and catabolism." (PMID 39156133, 2024).
lymphoma (3 papers, 2021 to 2025). A malignant (clonal) proliferation of B- lymphocytes or T- lymphocytes which involves the lymph nodes, bone marrow and/or extranodal sites. "Accumulating evidence indicates that TREM2+ macrophages drive immunosuppression, reduce response to ICIs, and cause poor prognosis in a variety of cancers, including lymphoma." (PMID 40268516, 2025).
metastatic tumors (3 papers, 2019 to 2025). "We found that myeloid components in human metastatic tumors were mainly composed of monocytes and TAMs, and all three TAM clusters highly expressed lipid-associated TAM markers (APOE, C1QA, and TREM2) and exhibited a pro-tumoral phenotype featured by CD206 (MRC1) expression." (PMID 40394007, 2025). "Clinical investigations may show if there are gender-specific differences in the efficacy of anti-TREM2 immunotherapy in the stages of metastatic disease." (PMID 36230558, 2022). "In addition, the analysis of TREM2 staining verified that TREM2 expression gradually decreased in the order non-tumor livers, primary tumors, and metastatic tumors." (PMID 30683932, 2019).
osteoarthritis (3 papers, 2024 to 2025). A noninflammatory degenerative joint disease occurring chiefly in older persons, characterized by degeneration of the articular cartilage, hypertrophy of bone at the margins and changes in the synovial membrane. "The triggering receptor for myeloid 2 (TREM2) expressed on the surface of mouse immune cells inhibits inflammation and modulates M2 macrophage polarization, ameliorating osteoarthritis pathology." (PMID 39851515, 2025).
osteosarcoma (3 papers, 2021 to 2025). A usually aggressive malignant bone-forming mesenchymal neoplasm, predominantly affecting adolescents and young adults. "More significantly, a battery of research on bioinformatics revealed that TREM2 is a prognostic biomarker for osteosarcoma microenvironment remodeling." (PMID 36844870, 2023). "In our study, embarking on a comparison between components of immunity and stroma in TME, differentially expressed genes (DEGs) are generated, which revealed that TREM2 may be a potential biomarker of TME remodeling in osteosarcoma." (PMID 36844870, 2023). "What is of interest is that, although TREM2 may mediate the immunosuppressive tumor microenvironment through macrophage M2 polarization, its expression level has positive relevance with the overall survival time of osteosarcoma patients." (PMID 36844870, 2023). "Therefore, TREM2 may be a potential indicator of remodeling of TME in osteosarcoma, which is useful and helpful in predicting the clinical prognostic outcome of OS patients and provide a unique perspective for immunotherapy for OS." (PMID 36844870, 2023).
pancreatic cancer (3 papers, 2019 to 2025). "This study uses biomaterial scaffolds to identify a macrophage gene signature defined by high expression of C1qa, C1qb, and Trem2 that is elevated systemically in mouse and human pancreatic cancer." (PMID 33782087, 2021). "While C1qa, C1qb, and Trem2 are known drivers of alternatively activated macrophage polarization in a LPS-induced inflammation model, little is known about their involvement in pancreatic cancer." (PMID 33782087, 2021). "ANXA1 supports an immunosuppressive TME, promoting M2 polarization represented by TREM2 TAMs mobilization, ANXA1 derived from cancer cells may be involved in the formation of a TME specific to pancreatic cancer." (PMID 41228323, 2025). "Paralleling the mouse data, C1QA, C1QB, and TREM2 were up-regulated in macrophages from human pancreatic cancer compared with macrophages from the non-malignant pancreas." (PMID 33782087, 2021).
pancreatic ductal adenocarcinoma (3 papers, 2025). An infiltrating adenocarcinoma that arises from the epithelial cells of the pancreas. "While, in pancreatic ductal adenocarcinoma, TREM2 deficiency promotes tumor progression through the expansion of proinflammatory macrophages and IL-1β–driven pathogenic inflammation." (PMID 41253786, 2025). "Single-cell sequencing demonstrated that Trem2 knockout enhances pro-inflammatory macrophages in pancreatic ductal adenocarcinoma and exacerbates pathogenic inflammation." (PMID 41305343, 2025).
parasite infection (3 papers, 2019 to 2025). "In the context of parasite infection, Trem2 promotes macrophage M2 polarization but suppresses M1 polarization." (PMID 40597375, 2025). "An emerging role for Trem2 in regulating immune functions of macrophages in infectious diseases, including bacterial, viral, and parasitic infections." (PMID 38317180, 2024). "In contrast, expansion of Plasmodium parasitemia was amplified in the absence of TREM2, and Kupffer cells lacking TREM2 expression had a more anti-inflammatory polarization." (PMID 31662766, 2019).
proteinopathies (3 papers, 2022 to 2025). "It is believed that TREM2 deficiency alters phagocytic clearance of TDP-43 by microglia which can account for the high inclusion density of glial cells in TDP-43 proteinopathies leading to enhanced neuronal damage." (PMID 36439561, 2022). "It remains unclear how TREM2 may mediate an influence on neurodegenerative disease, particularly in relation to key neuropathological hallmarks such as neuronal loss and proteinopathy." (PMID 40400621, 2025). "Studies are suggesting that people with certain gene mutations or variants in triggering receptor expressed on myeloid cells 2 (TREM2) and CD33, both highly expressed in microglia, have an increased risk of TDP-43 proteinopathies." (PMID 36439561, 2022). "Results suggest that being a carrier of mutations in MAPT, TARDBP, and TREM2 triggers and accelerates the development of FTD proteinopathies that, eventually, yield a more pronounced effect on the the cognitive, behavioral, and brain tissue impacts associated with FTD." (PMID 36474176, 2022).
sarcoidosis (3 papers, 2015 to 2023). Sarcoidosis is a multisystemic disorder of unknown cause characterized by the formation of immune granulomas in involved organs. "The aim of the study was to analyse TREM-1 and TREM-2 expression to identify further molecular mechanisms participating in the immunopathogenesis of sarcoidosis and HP." (PMID 32508528, 2020). "TREM-2 expression was increased in both, sarcoidosis and HP-sarcoidosis: median: 34.79; HP: median: 36.00; control: median: 12.98, (sarcoidosis versus control: p < 0.05; HP versus control: p < 0.05)." (PMID 32508528, 2020). "Triggering receptor expressed on myeloid cells-2 (TREM-2) is involved in cell fusion and granuloma formation, the characteristic sign of sarcoidosis." (PMID 26166951, 2015). "There is a possibility that increased TREM-2 expression and vitamin D-dependent antimicrobial mechanisms may be two parts of the immune response in sarcoidosis, in which the vitamin D level and TREM-2 expression somehow interact with each other." (PMID 26166951, 2015). "Differences in TREM receptor expression in sarcoidosis (increase in TREM-1 and TREM-2) and HP (increase in TREM-2) and correlation analysis suggests that activation via TREM may participate in typical immunological characteristics of sarcoidosis and HP." (PMID 32508528, 2020). "Increased expression of TREM-2 may be involved in macrophage fusion and granuloma formation by an increase in expression of mediators of macrophage fusion, such as DC-STAMP and cadherin-1 similar to sarcoidosis." (PMID 32508528, 2020).
scrapie (3 papers, 2019 to 2025). A fatal disease of the nervous system in sheep and goats, characterized by pruritus, debility, and locomotor incoordination. "We utilised the mouse-passaged ME7 scrapie strain to provide further insight into the role of TREM2 in disease pathogenesis." (PMID 40400621, 2025). "In mouse scrapie TREM2 overexpression, although playing a role in microglial activation, was found not to contribute to prion pathogenesis." (PMID 30705335, 2019).
Skin Cutaneous Melanoma (3 papers, 2021 to 2024). "And, high expression of TREM2 is associated with tumor-infiltrating immune cells (e.g., macrophages, B cells, CD8+ T cells, CD4+ T cells, DCs, etc.)and longer cumulative survival, playing a protective role in skin cutaneous melanoma." (PMID 38725629, 2024). "Similarly, the expression level of TREM2 is upregulated in skin cutaneous melanoma tissues." (PMID 38725629, 2024).
subarachnoid hemorrhage (3 papers, 2021 to 2024). A serious neurological disorder characterized by intracranial hemorrhage into the subarachnoid space. "The aim here was to investigate the neuroprotective role of TREM2 and its regulatory mechanism after subarachnoid hemorrhage (SAH)." (PMID 34458257, 2021).
type 2 diabetes (3 papers, 2021 to 2023). "This region has been associated with TREM2 levels, circulating Interleukin-1-receptor antagonist levels and triglyceride change in response to fenofibrate in statin-treated type 2 diabetes." (PMID 33846280, 2021).
acute lung injury (2 papers, 2023 to 2025). A condition of lung damage that is characterized by bilateral pulmonary infiltrates (pulmonary edema) rich in neutrophils, and in the absence of clinical heart failure. "In addition, grape seed proanthocyanidins orchestrate M2a macrophage polarization through the TREM2/PI3K/Akt pathway, thereby ameliorating LPS-induced acute lung injury." (PMID 40552184, 2025).
asthma (2 papers, 2017 to 2021). "Analysis of BALF from patients with asthma showed increased expression of TREM-2 which was associated with increased eosinophil and eosinophilic inflammation." (PMID 28928485, 2017). "Viral and bacterial infections, which are known to exacerbate inflammation and impair the lung response in respiratory diseases like asthma, have been associated with increase intracellular and cell surface levels of TREM-2 on macrophages." (PMID 28928485, 2017). "TREM2 down was associated with ‘Development_NOTCH‐induced EMT’ (P = 1.3E‐06), ‘Eosinophil granule protein release in asthma’ (P = 2.0E‐05), and ‘Signal transduction_Cyclic AMP signaling’ (P = 4.6E‐05)." (PMID 34523252, 2021). "The recently discovered triggering receptor expressed on myeloid cells (TREM)-2 has been shown to be expressed on DCs in several disease models, however, its role in asthma is yet to be elucidated." (PMID 28928485, 2017). "TREM2 up showed enrichment in ‘Immune response_TSLP signaling’ (P = 3.0E‐7), ‘Th2 cytokine‐induced alternative activation of alveolar macrophages in asthma’ (P = 1.1E‐06), and ‘Immune response_IL‐4‐induced regulators of cell growth, survival, differentiation, and metabolism’ (P = 1.2E‐06)." (PMID 34523252, 2021). "Although TREM-2 provides both activating and inhibitory signals in several disease models, little is known about its expression in the airways and it is still unclear if the receptor plays a role in the pathogenesis of asthma." (PMID 28928485, 2017).
bacterial pneumonia (2 papers, 2014 to 2024). Acute infection of the lung parenchyma caused by bacteria (e.g., Streptococcus pneumoniae, Haemophilus influenzae, Chlamydia pneumoniae, Mycoplasma pneumoniae, and Legionella pneumophila). "To investigate the role of pulmonary TREM-2 in the context of bacterial pneumonia, we first established which cell types expressed TREM-2 within the lungs." (PMID 24945405, 2014). "In this study we examined the effects of TREM-2 on bacterial phagocytosis and pulmonary inflammation within the context of bacterial pneumonia." (PMID 24945405, 2014). "However, in the bacterial pneumonia model induced by B. pseudomallei and Klebsiae pneumoniae, the number of neutrophils did not increase in Trem2-/- mice in the early stage of infection, suggesting that the effect of TREM2 on neutrophils recruitment is also bacteria specific." (PMID 38236825, 2024).
behavioral variant frontotemporal dementia (2 papers, 2019 to 2025). "Additionally, biallelic TREM2 variants contribute to recessively inherited early-onset behavioral variant frontotemporal dementia with white matter abnormalities but without bone involvement, while monoallelic missense variants in TREM2 significantly increase the risk of AD." (PMID 40301889, 2025).
cardiac hypertrophy (2 papers, 2025). "Trem2-deficient mice also exhibit exacerbated cardiac hypertrophy and a decrease in cardiac capillary density." (PMID 40083551, 2025). "TREM2-/- mice exhibit obvious symptoms, such as cardiac hypertrophy, diastolic dysfunction, renal injury and decreased cardiac capillaries density, further highlighting the significant role of TREM2 in cardiovascular diseases." (PMID 40242752, 2025).
corneal infection (2 papers, 2017 to 2018). A viral or bacterial infectious process affecting the cornea. "In summary, we demonstrated that TREM2 deficiency increased host susceptibility to P. aeruginosa corneal infection in C57BL/6 mice." (PMID 29887864, 2018). "Together, these results suggested that TREM2 promoted host resistance to P. aeruginosa corneal infection in C57BL/6 mice." (PMID 29887864, 2018). "TREM2 deficiency also resulted in increased levels of IFNγ, TNFα and iNOS following colonic mucosal injury and TREM2 knockdown or antibody-mediated inhibition increased expression of many inflammation-related cytokines following corneal infection." (PMID 28768545, 2017).
E. coli infection (2 papers, 2022 to 2024). "Transfer of TREM2-overexpressing BMDMs enhances the clearance of Escherichia coli, while unaltered bacterial counts in WT and TREM2–/– mice following E. coli infection are also reported, suggesting the complexity of TREM2 function in E. coli elimination." (PMID 39405126, 2024). "In contrast, evidence also exists that TREM2 suppresses ROS levels in murine models during E. coli infection." (PMID 35924849, 2022). "TREM2 is involved in intracellular ROS production during infection with Salmonella enterica serovar Typhimurium or Pseudomonas aeruginosa, whereas during Escherichia coli infection, overexpression of TREM2 resulted in decreased ROS." (PMID 35924849, 2022).
fibrosarcoma (2 papers, 2022 to 2023). A malignant mesenchymal fibroblastic neoplasm affecting the soft tissue and bone. "One study identified two populations of tumor-infiltrating myeloid suppressive cells that express TREM2 in a subcutaneous MCA-205 fibrosarcoma model: a TAM population and a myeloid regulatory cell population." (PMID 36119485, 2022). "In another study utilizing subcutaneous injection of MCA-205 fibrosarcoma cells in Trem2-/- mice, the investigators not only observed a reduction in tumor growth, but also an expansion of the natural killer and cytotoxic T cell population accompanied by a decrease in dysfunctional CD8+ T cells." (PMID 36119485, 2022). "A recent study using a murine fibrosarcoma model showed that the tumor on Trem2 KO mice grew much slower than the tumor on WT mice, consistent with our original hypothesis that the expression of TREM2 on immunosuppressive myeloid-origin cells could facilitate the growth of tumors." (PMID 37029450, 2023).
fungal infection (2 papers, 2024 to 2025). "Notably, targeting TREM2 enhanced the antifungal immune response in vivo and in vitro, thereby alleviating the severity of CARD9-deficient subcutaneous dematiaceous fungal infection." (PMID 41329515, 2025). "However, the functional role and mechanism of Trem2 during fungal infection in interstitial macrophages remain unclear." (PMID 38317180, 2024).
gastric adenocarcinoma (2 papers, 2021). "About 90% of gastric adenocarcinoma are associated with HP infection 48, TREM2 is not only associated with chronic inflammation and OS of GC patients, but also involve in carcinogenesis of some other tumors 11,17,19,47." (PMID 33976737, 2021).
Hepatitis (2 papers, 2017 to 2021). Inflammation of the liver. "TREM-2 KO mice were protected from lymphocytic choriomeningitis virus–induced hepatitis and showed improved virus control despite comparable virus-specific T cell responses." (PMID 34878838, 2021). "Mice lacking the lipid-sensing surface receptor triggering receptor expressed on myeloid cells 2 (Trem2−/−) were protected from LCMV-induced hepatitis and showed improved virus control despite comparable virus-specific T cell responses." (PMID 28900132, 2017). "Non-hematopoietic expression of TREM2 was found to be responsible for aggravated hepatitis, indicating a novel role for TREM2 in the non-myeloid compartment." (PMID 28900132, 2017). "In order to investigate the induction of cytokines before the peak of LCMV-induced hepatitis, we quantified protein concentrations of chemokine (C-X-C motif) ligand 1 (CXCL1), interleukin 6 (IL-6) and interferon alpha (IFNα) in sera of WT and Trem2−/− mice by ELISA." (PMID 28900132, 2017).
influenza (2 papers, 2023 to 2024). An acute viral infection of the respiratory tract, occurring in isolated cases, in epidemics, or in pandemics; it is caused by serologically different strains of viruses (influenzaviruses) designated A, B, and C, has a 3-day incubation period, and usually lasts for 3 to 10 days. "There were trends to suggest reduced microglial activation following influenza vaccine in TREM2 carriers." (PMID 37990275, 2023).